ANKRD18A (ankyrin repeat domain 18A)
Synonyms: KIAA2015; FLJ35740; FAM95C
Tractability: PROTAC: ubiquitination databases record sites on it.
Gene: Protein-coding gene on chromosome 9 (38,540,567 to 38,620,596, reverse strand). Ensembl gene ENSG00000180071.
Genetic constraint (gnomAD): Loss-of-function variants: 59 observed, 84 expected, observed/expected ratio (o/e) 0.7, 90% interval 0.57 to 0.87. The upper end of that interval is the gene's LOEUF score, 0.87, which puts it in group 3 of 6, group 1 being the genes least tolerant of losing a copy. Missense variants: 900 observed, 1,031.4 expected, observed/expected ratio (o/e) 0.87, 90% interval 0.82 to 0.92. Synonymous variants: 295 observed, 358.86 expected, observed/expected ratio (o/e) 0.82, 90% interval 0.75 to 0.9.
Homologues: Orthologues: chimpanzee ANKRD18A (97% identical), tropical clawed frog ankrd7 (23% identical), Caenorhabditis elegans lem-3 (11% identical), Drosophila melanogaster CG8679 (10% identical), zebrafish si:ch211-272n13.3 (9% identical), Caenorhabditis elegans F44E5.15 (4% identical), Drosophila melanogaster CG42391 (4% identical), Caenorhabditis elegans K07D4.2 (2% identical). Paralogues in human: ANKRD18B (93% identical), ANKRD26 (46% identical), ANKRD20A1 (35% identical), ANKRD62 (24% identical), ANKRD30B (24% identical), ANKRD30A (24% identical), ANKRD30BL (11% identical).
Diseases named in the same sentence as ANKRD18A in open-access papers:
ANKRD18A is named in the same sentence as 2 diseases in open-access papers, as found by Europe PMC text mining. Sharing a sentence is not in itself a finding about the gene and the disease. The quoted sentences say what the papers report.
liver cancer (1 paper, 2024). An epithelial or non-epithelial malignant neoplasm that arises from the liver. "The key nodes in the miR-936/Pim-3/ANKRD18A/Src/NRF2 axis that regulate ferroptosis resistance in liver cancer should also be further determined." (PMID 39507762, 2024). "Therefore, Pim-3, whose expression was positively correlated with low a miR-936 level, suppressed ferroptosis in sorafenib-resistant liver cancer cells by accelerating the activation of the ANKRD18A/Src/NRF2 pathway." (PMID 39507762, 2024). "In addition, it is reasonable to conclude that Pim-3 upregulation mediated by a low miR-936 expression promotes sorafenib resistance in liver cancer by inhibiting ferroptosis, in which the activation of the ANKRD18A/Src/NRF2 pathway, especially the transcriptional activity of NRF2, is essential." (PMID 39507762, 2024).
ANKRD18A also shares sentences with these, for which no sentence is quoted: cancer (2 papers).